CD4 (CD4 molecule)
Diseases named in the same sentence as CD4 in open-access papers (continued):
Sharing a sentence is not in itself a finding about the gene and the disease.
tumor (continued). "The tumor microenvironment conditions promote the differentiation of memory and naïve CD4 + T cells into CD4 + T regulatory cells which suppress antitumor immunity." (PMID 35858901, 2022). "We found that IL1R1+ Treg cells were more effective than their IL1R1− counterparts at suppressing proliferation of CD8+ and CD4+ responder T (Tresp) cells isolated from tumours as well as from peripheral blood." (PMID 35545675, 2022). "Th9 cells, IL-9 producing CD4+ T cells, are closely related to Th2 cells and contribute to allergic inflammation and anti-tumor immunity." (PMID 35432341, 2022). "It is well known that CD8 T cells are essential for immune mediated tumor cell kill, but more recently CD4 T cells have been recognized as critical players in a variety of cancer models." (PMID 36385142, 2022). "Compared to positive drug and blank control groups, proportions of tumor-infiltrating CD3+CD4+ and CD3+CD8+ T cells were significantly increased after in vivo administration of HGWD for a period of time." (PMID 36313348, 2022). "Subsequently, neutrophils increase the number of CD8+, CD4+T cells, and B cells in the tumor and promote the release of IFN-γ, TNF-α, and IL-12; thus, the antitumor immunity and anticancer effect was enhanced." (PMID 36034656, 2022). "We further tested the effects of IU1 and Epacadostat on CD8+ T cells and CD4+ T cells isolated from the spleens of MC38 tumor-bearing C57BL/6 J mice." (PMID 36163134, 2022). "Consistent with these observed therapeutic benefits, the combination therapy was associated with an expansion of CD4+ T, CD8+ T, CD3-NK1.1+ (NK), and CD3+NK1.1+ (NKT cells, NKT) cells in the blood day 13 post tumor implantation." (PMID 35304456, 2022). "It has been established that CD4+ T cells can act directly by killing tumor cells through cytolytic mechanisms or indirectly by modulating the tumor microenvironment." (PMID 36297616, 2022). "Here, we summarized and discussed the critical role of DOCK8 in cytoskeleton reconstruction, CD4+ T cell differentiation, immune synaptic formation, tumor immune infiltration, tumor immune surveillance and tumorigenesis." (PMID 36386145, 2022). "The results showed that lncRNAs with different expression levels were positively correlated with tumor-infiltrating immune cells such as CD4+ T cells, CD8+ T cells, and NK cells but negatively correlated with hematopoietic stem cells and neutrophils." (PMID 35249533, 2022). "Together with CD4+ T cells, they can be functionally impaired by cancer cells themselves or the composition of the tumour microenvironment with strong contribution of adjacent platelets." (PMID 35285006, 2022). "In a cancer setting, CD4+ T cells orchestrate anti-tumor immune responses by activating CTLs in tumors via production of IL-2 and IFN-γ." (PMID 36005179, 2022). "Our findings provide an approach for isolating tumor-reactive CD4+ Th TILs directly ex vivo that will help define their role in the antitumor immune response and potentially improve future adoptive T cell therapy approaches." (PMID 35439168, 2022). "Generally, the antigen presentation pathway in a tumor microenvironment is enhanced followed by the activation of immune cells, especially CD4+ and CD8+ T cells." (PMID 35433435, 2022). "Depletion studies revealed that CD8 T cells were ultimately required for treatment efficacy, but CD4 T cells and NK cells also partially contributed to tumor control." (PMID 36056093, 2022). "Treg cells, another subset of CD4+ T cells, are responsible for immunosuppression and help tumor cells avoid immune surveillance." (PMID 36246629, 2022). "We examined the correlation between PAQR5 expression and the degree of infiltration of six immune cell subtypes (CD8+ T cells, CD4+ T cells, B cells, DCs, macrophages, and neutrophils) by TIMER and its association with tumor purity." (PMID 36119517, 2022).
tumor (continued). "DCs activated with mRNA or protein encodes/incorporates a diversified repertoire of tumor epitopes elicit MHC class I- and II- biased immunity respectively, which eventually leads to a differential activation preference for CD8+ T and CD4+ T cells." (PMID 35547749, 2022). "Among them, the levels of four kinds of tumor-infiltrating immune cells—M0 macrophages, M2 macrophages, CD4+ T cells, and CD8+ T cells—were elevated in humans, with macrophages the most abundant population in the infiltrated immune cells." (PMID 35326625, 2022). "The high density of tumor-associated macrophages as the immunosuppressive element is linked to the increased tumor recurrence rate of CCA, while the presence of CD4+ and CD8+ T cells has a significant relationship with favorable prognosis in CCA." (PMID 35847907, 2022). "Mitochondria‐targeted atovaquone (Mito‐ATO) in situ vaccination eliminates tumor cells by activating systemic CD4+ T response through blocking both granulocytic‐myeloid‐derived suppressor cells (G‐MDSCs) and regulatory T cells (Tregs)." (PMID 35243806, 2022). "In a mouse model of NSCLC, the presence of both neoantigen-reactive CD4 Th cells and B cells in the tumor was shown to be beneficial for the anti-tumor immune response." (PMID 35937775, 2022). "CD4+ T cells display an antitumor immunity profile by enhancing the antineoplastic effect at the tumor site, preventing activation-induced cell death, and giving priority to the generation of immune memory cells by cytotoxic T-lymphocytes." (PMID 35122478, 2022). "Extending from the nanoagonist-enhanced T cell priming capacity of DCs, we further measured the activated T cell populations (CD4/CD8 T cells) in tumor tissues and spleens after different treatment via immunofluorescence imaging and flow cytometry." (PMID 36167857, 2022). "We found that a positive correlation between the high-risk group and tumor-infiltrating immune cells, such as neutrophils and monocytes, was negatively correlated with CD8+T cells and CD4+ cells." (PMID 35852867, 2022). "Higher numbers of CD4+ T cells can improve survival and patient benefits, whereas infiltrated inefficient T cells can drive tumor immune resistance." (PMID 35664768, 2022). "CD38 expression, a T cell activation marker with conflicting roles in tumor immunology, was diminished in edited CD4+ and CD8+ TILs (p ≤ 0.0001 and p ≤ 0.0098, respectively)." (PMID 35141398, 2022). "It has been previously demonstrated that there is an interplay between T cells and tumor vascularization inducing CD4+ T-cell activation, IFNγ production, and subsequent boosting angiogenesis homeostasis, but also immune response." (PMID 36294987, 2022). "Two years later, the fifth follow-up CT revealed that the T11 tumor shrank in size to 6 cm3 when the CD4 count reached 186 cells/μL, which was the highest value during his treatment." (PMID 35141174, 2022). "Analysis of tumor-infiltrating lymphocytes (TILs) showed that more CD4, CD8, neutrophil, macrophages, and dendritic cells were detected in high prognostic risk LUSC patients compared to low prognostic risk LUSC patients." (PMID 36131791, 2022). "It was discovered that cryo-thermal therapy remodeled the tumor microenvironment and induced an antigen-specific CD4+ T-cell response, which mediated stronger antitumor immunity in vivo." (PMID 35874660, 2022). "Ramamoorthi G observed that HER2-DC1 combined with T-DM1 increased the levels of tumor-infiltrating CD4 and CD8 T, B, natural killer T, and NK cells in HER2 breast cancer-bearing mice and promoted complete tumor regression." (PMID 36601109, 2022).
tumor (continued). "Briefly, there were very few CD3/CD8/CD4 positive TILs (tumor infiltrating lymphocytes) in Pt204’s primary lesion, whereas the obviously elevated degrees of infiltration of CD3, CD8 or CD4 positive lymphocytes were observed in her metastases of M1-M5." (PMID 34255132, 2022). "A link between high microbial diversity, enhanced tumor infiltration of CD4+ lymphocytes, and CD4 cell activation during radiation therapy was observed." (PMID 35625485, 2022). "Activated, central/effector memory CD4/8 T cells were previously demonstrated to play a positive role in promoting tumor immune responses." (PMID 35884556, 2022). "We further investigated the presence of cytotoxic CD4+ T cells and HLA-II-expressing tumor cells in treatment-naive NSCLC samples using immunofluorescence." (PMID 35831288, 2022). "Although CD8+ T cells are recognized as the major effector cells in tumour elimination, CD4+ T cell help is critical in facilitating an effective anti-tumour immune response." (PMID 36259237, 2022). "ATS status defines an inflamed yet exhausted tumor microenvironment, in which the activities of the exhausted CD8+ or CD4+ T cells were strongly associated with ATS." (PMID 36302799, 2022). "An important role in the process of tumor growth is attributed to CD4+ and CD8+ lymphocytes and the cytokines secreted by these cells." (PMID 36362598, 2022). "Altogether, these data show that IFNγ production by CD4 T cells upon antigen encounter on TAM in the tumor microenvironment is responsible for both the TAMs functional switch and the antitumor effect." (PMID 35903540, 2022). "It has been demonstrated that the tumor-derived TGF-β induced extrathymic conversion of naïve CD4+ T cells induces Foxp3+ Tregs." (PMID 36358638, 2022). "TIMER2.0 gives the estimation of purity (percentage of malignant cells in a tumor tissue) and abundances of six immune infiltrates (B cells, CD4+ T cells, CD8+ T cells, neutrophils, macrophages, and dendritic cells)." (PMID 35954424, 2022). "Both CD8+ and CD4+ neoAg-specific T cells contribute to lasting tumor clearance, and work continues to develop strategies to promote maximal cytotoxic T cell responses." (PMID 35432319, 2022). "For example, anti–PD-1 antibodies increase the number CD4+ cells, which normalizes tumor blood flow, allowing more drug to reach the tumor tissues, and long-term use of enfortumab vedotin makes tumor tissue sensitive to CCs." (PMID 36292976, 2022). "This patient also experienced the second largest increase in CD8+ T cells as well as the greatest decrease in CD4+ regulatory T cells, potentially indicating a pro-inflammatory response to—or despite—increased neoplastic tumor cell density." (PMID 35217711, 2022). "For instance, CD8+ cytotoxic T cells, CD4+ T helper cells, natural killer cells, and M1 macrophages have tumor-antagonizing effects, whereas Treg cells and M2 macrophages are tumor-promoting cells." (PMID 36291773, 2022). "The high-risk subgroup positively correlated with tumor-infiltrating immune cells such as cancer-related fibroblasts, T cell CD8+, M2 macrophages, and macrophage and was negatively associated with T cell CD4+ and T cell follicular helper cells." (PMID 35814472, 2022). "In a previous study, MHC class II on HRS cells was a predictive marker for CR and prolonged progression-free survival in patients with HL after PD-1 blockade, suggesting the importance of CD4+ T cells in the tumor environment of CHL." (PMID 36035394, 2022). "In a murine model of sarcoma, it was demonstrated that the recognition of tumor cell peptides presented on MHC II by CD4+ T helper cells was crucial for the generation of a functional CD8+ T cell response in immune checkpoint inhibition." (PMID 36612283, 2022). "On the contrary, IgG2a Fc domain conjugation to the Fab fragment reduced tumor burden, depleted intra-tumoral Tregs, and expanded CD4+ effector T-cells." (PMID 35326731, 2022).
tumor (continued). "In the process of tumour growth, specifically for PC, CD4(+) T cells differentiate into regulatory T (Treg) cells due to the demand for abundant energy demands and biological raw materials." (PMID 36578477, 2022). "The results demonstrated that high Rab37 expression showed concordantly increased CHI3L1 level in the tumor infiltrated CD4+ T cells, CD8+ T cells and F4/80+ macrophages." (PMID 34987649, 2022). "scRNAseq identified various cell populations within the tumor and its microenvironment, such as endothelial cells, keratinocytes, fibroblasts, CD4+/CD8+ T cells, myeloid cells, and epithelial cells." (PMID 36307545, 2022). "Further, we analyzed the status of CD4+ T cells to predict the status of an adaptive anti-tumor immune response." (PMID 35135586, 2022). "The anti-CD4 antibody did not affect tumor progression in both CL-Can and PBS-Can although the anti-CD4 antibody depleted CD4+ T cells from tumor tissue." (PMID 36470862, 2022). "ABNM@TMZ/OTX also increased both the percentage and absolute numbers of activated CD8+ and CD4+ T cells in blood and tumor, confirming that prevention of GBM re‐occurrence was achieved by activating anti‐tumor immune responses together with TMZ chemotherapy." (PMID 37325609, 2022). "An analysis of six tumour-infiltrating immune cells (B cells, CD4+ T cells, CD8+ T cells, neutrophils, macrophages and dendritic cells) was conducted." (PMID 35592424, 2022). "OVs also induce T cell responses in tumors, which can promote local inflammation and recruit CD4+ and CD8+ T cells associated with an anti-tumor response." (PMID 36293504, 2022). "In brief, in IM, frequent proximity of CD4+ Treg to tumor cells promoted the recurrence of locally advanced NSCLC patients." (PMID 36685566, 2022). "We found that high infiltration of CD8-positive T cells in tumor tissue, high expression of CD68-positive tumor-associated macrophages, and low expression of CD4-positive T cells was significantly associated with good response to ICI treatment and survival." (PMID 36437290, 2022). "Although CD8 cytotoxic T lymphocytes (CTLs) are the main cells involved in tumor cell killing, previous studies have reported the imperative roles of the CD4 T cells in orchestrating antitumor response." (PMID 37529004, 2022). "It is further noted that the TAMCs subset expressing alpha E integrin, namely CD103+ TAMCs, appeared more actively to interact with CD4+ T cells and located closer to tumor cells than their CD103- counterparts." (PMID 36168626, 2022). "Other tumor-infiltrating immune cells, such as CD4+ T cells, CD8+ T cells, B cells, NK cells, M-MDSCs and granulocytes (Ly-6G+) were also evaluated in the peripheral and central part of B16 tumors." (PMID 36213072, 2022). "The protumour vs. antitumour roles of helper and regulatory CD4 T-cell subsets have been extensively studied in different tumour types." (PMID 35572552, 2022). "CD4+ was higher in tumor samples from women compared to men (22.04% vs. 10.26%, p=0.002) and also in lymph node samples (39.54% vs. 8.56%, p=0.001)." (PMID 36387163, 2022). "This treatment led to an accumulation of tumor-infiltrating effector CD4+ and CD8+ T cells and CD206-CD103+ cross-presenting DCs." (PMID 35572601, 2022). "The adaptive immune response in patients with HCC is weakened with exhaustion or dysfunction of tumor-infiltrating lymphocytes, particularly CD4+ and CD8+ T cells." (PMID 36466855, 2022). "Tumor-infiltrating CD4+T cells and CD8+T cells were correlated with superior prognosis of breast cancer, colorectal cancer, glioblastoma, and cervical cancers." (PMID 35586567, 2022). "CD4+ T cells belong to the family of tumor necrosis factor receptor costimulatory receptors and are associated with NSCLC tumor frequency." (PMID 36110123, 2022). "Currently, CD4 + T cells have received more and more attention, but their function in anti-tumor immunity is bidirectional." (PMID 35879796, 2022).
tumor (continued). "A recent study demonstrated that immunotherapy is triggered by the activation of peripheral CD4+ T cells and subsequent killing of tumour cells." (PMID 35488454, 2022). "Future studies should investigate if the presence of PD-1+CD4+ T cells correlates with progression to tumor stage disease." (PMID 35406628, 2022). "A slight increase in CD8+ T cells was observed as tumor stages progressed, which is accompanied with minor augment of activated CD4+ T cell numbers." (PMID 35990685, 2022). "CD4 T cells are also known to show direct tumor cytotoxicity and are indirectly involved in the generation of a humoral response." (PMID 35651802, 2022). "The significance of the CD4+/CD8+ ratio has been explored in a high number of tumor types resulting in very different prognostic significance." (PMID 35454849, 2022). "TILs are a heterogeneous mixture of lymphocytes composed mainly of anti-tumor effector T cells (CD4+ and CD8+ subpopulations) and immunosuppressive Treg cells." (PMID 35874729, 2022). "We confirmed the same tendency in the amount of detected EBV genetic material in the tumor and lymph node samples and the level of PD-1 expression on the CD4+ and CD8+ T cells in all samples." (PMID 35158748, 2022). "Clinical-pathological evaluations, survival at follow-up, immunophenotyping of leukocytes in peripheral blood and tumours, and immunohistochemical evaluation of CD4+, granzyme B, perforin and FAS-L were performed." (PMID 35512031, 2022). "We detected lower frequencies of CD4+ and CD8+ T cells in dLNs but increased frequencies of Tregs in tumor bearing Asm-deficient mice compared to WT mice." (PMID 36426850, 2022). "Tumor cells induce the release of TGF-β by DCs which promotes the conversion of naïve CD4+ T cells into Tregs." (PMID 36578789, 2022). "Blocking TGF-β signaling has been demonstrated to boost tumor control via targeting tumor stromal compartment or CD4+ T cell-mediated blood vasculature remodeling." (PMID 36229613, 2022). "Our work also demonstrates that CDDO-Me alters the tumor T cell compartment by increasing the ratio of CD8 to CD4 T cells and by reducing Treg tumor infiltration." (PMID 35265066, 2022). "We found that higher levels of tumour-infiltrating T cell subsets, including CD8+PD-1+LAG-3+TIM-3+, CD4+FoxP3+CTLA-4+ T and CD68+STING+ cells, were associated with inferior overall survival (OS) in 80 patients." (PMID 35982052, 2022). "As a result, the number of both activated endogenous and exogenous DCs, the number of DCs migrated to lymph nodes, and the tumor infiltration of CD4+ and CD8+ T cells are remarkably high in the (oAd + DC/gel) samples." (PMID 35273607, 2022). "CD4+ T cells have both tumor-inhibiting activity and tumor-promoting activity, depending on the cell subpopulation type and immune microenvironment." (PMID 36591220, 2022). "Tumor-associated antigens and neoantigens released by the dying cells cultivate tumor antigen-specific CD4+ and CD8+ T cell responses." (PMID 36090051, 2022). "PD-L1 and PD-L2 bind PD-1 expressed on tumor-infiltrating CD4 and CD8 T cells, inactivating them in the TME." (PMID 36119020, 2022). "The HL specific tumor microenvironment (TME) consists mainly of CD4+ T cells placed around HRS-cells, CD4+—T regulatory (T-reg) cells, macrophages, eosinophils, mast cells, NK cells, fibroblasts." (PMID 36362802, 2022). "In contrast, both tumor types contained low percentages of cytotoxic cells, but contained substantial percentages of Cd4+ T cells." (PMID 35600339, 2022). "To explore the contribution of different components of the immune response to tumor rejection, we also depleted CD4+ or CD8+ T cells starting 1 day before tumor challenge in additional pBARF1 immunized groups." (PMID 35071745, 2022). "(D) MC38 OVA tumor cells were implanted subcutaneously in WT and Piezo1-/- mice (n=10) and at day 20, the CD45.1+ donor CFSE+OTII CD4+T cells were transferred into WT and Piezo1-/- tumor-bearing mice for 10 days." (PMID 35993548, 2022).